MIR101-1 (microRNA 101-1)
Synonyms: hsa-mir-101-1; MIRN101-1; mir-101-1
Gene: MicroRNA gene on chromosome 1 (65,058,434 to 65,058,508, reverse strand). Ensembl gene ENSG00000199135.
Gene Ontology:
Biological process: miRNA-mediated post-transcriptional gene silencing
Cellular component: RISC complex
Homologues: Orthologues: chimpanzee ptr-mir-101-1 (99% identical), dog MIR101-1 (99% identical), macaque mml-mir-101-1 (99% identical), mouse Mir101a (99% identical), pig ssc-mir-101-2 (99% identical), rabbit MIR101-1 (99% identical), tropical clawed frog xtr-mir-101a-2 (97% identical), guinea pig MIR101-1 (95% identical), zebrafish mir101a (93% identical). Paralogues in human: MIR101-2 (79% identical).